AURKA (aurora kinase A)
Diseases named in the same sentence as AURKA in open-access papers (continued):
Sharing a sentence is not in itself a finding about the gene and the disease.
sarcoma (5 papers, 2017 to 2025). A usually aggressive malignant neoplasm of the soft tissue or bone. "The expression of Aurora kinase A and B mRNAs was low in normal muscle tissue compared to sarcoma cell lines." (PMID 32138169, 2020). "In addition, AURKA accumulation, at the midzone and midbody region, in late mitosis of tetraploid sarcoma cells also indicates that its Apc/C-cdh1 mediated proteolysis is deficient in these cells." (PMID 28035071, 2017). "We then confirmed the heterogeneous expression of AURKA and AURKB in nine sarcoma cell lines, both at genomic and protein levels." (PMID 32138169, 2020). "Recently, a dual inhibition of AURKA and AURKB shown efficiency on several cancer cell lines, including sarcomas and a promising Phase II study was done on metastatic sarcomas." (PMID 32138169, 2020). "We report in this work the effect of AURKA and AURKB inhibition by AMG 900, doxorubicin or both in different sarcoma cell lines, focusing on 4 dedifferentiated liposarcomas." (PMID 32138169, 2020).
thyroid cancer (5 papers, 2018 to 2023). "Also, AURKA (Aurora kinase A), a gene that encodes for a serine/threonine kinase needed for G2/M transition, mitosis, and cytokinesis, has been found overexpressed in thyroid cancers and numerous cancer types." (PMID 30911297, 2019). "We also performed phospho-mass spectrometry in AURKA knockdown thyroid cancer cells and control cells." (PMID 36471438, 2022). "According to in vitro data, AURKA knockdown markedly suppressed thyroid cancer progression in a nude mouse xenograft model." (PMID 36471438, 2022). "A previous study reported that the AURKA inhibitor MLN8237 inhibits thyroid cancer growth by promoting the proteasomal degradation of c-Myc." (PMID 36471438, 2022). "To explore the mechanism of the oncogenic role of AURKA in thyroid cancer cells, we performed whole transcriptome sequencing (RNA-seq) in AURKA knockdown cells and control cells." (PMID 36471438, 2022). "Similar results of the CUDC-907-mediated blockage of the S and G2/M phases were shown for pancreatic and thyroid cancers via the downregulation of the cell cycle regulators cyclin B1, AURKA, and PLK1." (PMID 35205815, 2022). "(2016), AURKA was further identified as an ‘extremely highly expressed cancer/testis gene’ of thyroid cancer." (PMID 30386706, 2018). "Future work may determine whether AURKA inhibition enhances sensitivity to AKT inhibitors in thyroid cancer." (PMID 36471438, 2022). "Furthermore, eight pairs of thyroid cancer and adjacent normal tissues were selected to detect the expression of AURKA by western blotting." (PMID 36471438, 2022). "Thyroid cancer tissues showed higher AURKA expression than adjacent normal tissues." (PMID 36471438, 2022). "Previous studies have indicated that AURKA is overexpressed in thyroid cancer tissues and cell lines, indicating that it could be helpful for diagnosis and therapy in thyroid cancer." (PMID 36471438, 2022). "Therefore, MYC-driven AURKA signalling may constitute a positive feedback loop that helps to continuously activate the PI3K/AKT pathway in thyroid cancer." (PMID 36471438, 2022). "Moreover, the malignant phenotypes induced by AURKA overexpression were partly blocked by AKT inhibitors and mTOR inhibitors, indicating that the oncogenic role of AURKA in thyroid cancer cells partly depends on the PI3K/AKT signalling pathway." (PMID 36471438, 2022). "A previous study showed that one AURKA inhibitor, MLN8237, had antitumor effects in thyroid cancer with high c-Myc expression but not in thyroid cancer with low c-Myc expression, suggesting that targeting AURKA may be an effective therapeutic strategy for c-Myc-overexpressing thyroid cancers." (PMID 36471438, 2022).
chronic myeloid leukemia (4 papers, 2015 to 2025). "In the context of resistance to TKIs, an AURKA/AURKB inhibitor has been reported to induce senescence in chronic myeloid leukemia cells carrying the imatinib-resistant T315I mutation in ABL50." (PMID 31000705, 2019). "In chronic myeloid leukemia (CML), the BCR-ABL oncoprotein upregulates AURKA and AURKB via the Akt signaling pathway, promoting leukemogenesis." (PMID 41296411, 2025).
ciliopathies (4 papers, 2020 to 2024). "Our findings confirm that ciliopathies can result from an excess of PIP2 and indicate that ciliopathies could be ameliorated by AurkA and HDAC6 inhibitors." (PMID 35079141, 2022). "Because AURKA is also associated with both cancer and ciliopathy, these findings suggest that the involvement of KCTD17 and USP8 in cancer and ciliopathy might be mediated by effects on ciliogenesis via a TCHP–AURKA pathway." (PMID 32825105, 2020). "Thus, a combination of these techniques is likely to advance our understanding of the mechanisms regulating AURKA and AKT kinase signaling within and around primary cilia and may pave the way for the development of novel therapeutics for ciliopathies." (PMID 34944109, 2021). "We then found that AURKA and AKT interact in diseased tissue in models of both ciliopathies and that the striking prevention of cyst formation observed upon co-deletion of Aurka, is associated with normalisation of AKT signalling, which occurs independent of AURKA’s kinase activity." (PMID 38191531, 2024).
colorectal adenocarcinoma (4 papers, 2020 to 2026). The most common type of colorectal carcinoma. "Korean colorectal adenocarcinoma patients may benefit from a AURKA level in order to predict poor outcomes." (PMID 38212708, 2024). "We found that among the 12 central genes, CCNA2, MAD2L1, DLGAP5, and AURKA were associated with the overall survival of colorectal adenocarcinoma (P < 0.05), and RRM2 and AURKA were associated with disease-free survival of colorectal adenocarcinoma (P < 0.05)." (PMID 33519906, 2020).
gastric adenocarcinoma (4 papers, 2012 to 2025). "Furthermore, inhibition of UBE2C expression was shown to reduce the level of phosphorylation of AURKA and impair cell viability in gastric adenocarcinoma cells." (PMID 37377594, 2023). "Also, the sensitivity and specificity of the expression changes of the AURKA, CEP55, DTL, and TTK genes for distinguishing colorectal and gastric adenocarcinoma from normal tissue were evaluated by ROC analysis." (PMID 40723362, 2025).
hepatoblastoma (4 papers, 2019 to 2025). Hepatoblastoma (HB) is a malignant hepatic tumor and is the most common pediatric liver cancer. "Meanwhile, LIN28B and AURKA expressions were upregulated in a transcriptomic and genomic analysis of human hepatoblastoma, and miRNA-26-5p inhibited hepatoblastoma by repressing LIN28B44." (PMID 32284747, 2020). "In addition, we examined the two other HSP90 client proteins involved in the cell cycle and hepatoblastoma, namely the polo-like kinase 1 (PLK1) and the aurora kinase A (AURKA)." (PMID 40282517, 2025).
invasive breast carcinoma (4 papers, 2016 to 2024). A carcinoma that infiltrates the breast parenchyma. "Importantly, AURKA has been found to be associated with an increased risk of invasive breast cancer among postmenopausal women." (PMID 38166892, 2024). "This hypothesis was further confirmed by a strong correlation (Pvalue = 0.04295) between AurkA and miR-128 expression in a subset of primary ductal invasive breast cancers (N = 32) by IHC." (PMID 27341528, 2016). "Our analyses of gene expression databases identify AURKA as the gene with the highest correlation with CSE1L in multiple cancer types, with breast invasive carcinoma data displaying the highest significance." (PMID 36797043, 2023).
liver fibrosis (4 papers, 2023 to 2026). "Here, we aim to investigate the role of AURKA in liver fibrosis and elucidate its underlying mechanism." (PMID 39834933, 2024). "Pharmacological inhibition of AURKA phosphorylation also resulted in reduced liver fibrosis in vivo." (PMID 39834933, 2024). "This study aimed to investigate the impact and underlying mechanism of AURKA on liver fibrosis and to assess the therapeutic potential of MLN8237, a small-molecule AURKA inhibitor, in preventing liver fibrosis in mice." (PMID 39834933, 2024). "Our findings from primary mouse HSC differentiation experiments showed a notable increase in both AURKA and α-SMA at day 5 compared to day 0, suggesting a potential role for AURKA in HSC activation during liver fibrosis." (PMID 39834933, 2024). "The results showed that AURKA was positively correlated with the progression of liver fibrosis and was predominantly expressed in activated HSCs." (PMID 39834933, 2024). "Future research is necessary to further elucidate the role of AURKA in liver fibrosis induced by various etiologies, as well as to investigate the intricate regulatory relationship between AURKA and Wnt/β-catenin both in vivo and in vitro." (PMID 39834933, 2024). "RNA interference and AURKA antagonism were used to examine the effects of AURKA on liver fibrosis, while RNA-sequencing, qRT-PCR, and western blotting were employed to elucidate the potential molecular mechanisms of AURKA on hepatic stellate cell activation." (PMID 39834933, 2024). "We observed significant changes in AURKA expression in patients with liver fibrosis and a history of alcohol consumption." (PMID 36778123, 2023). "Furthermore, targeting AURKA with MLN8237 has shown promising results in reducing liver fibrosis and HSC activation both in vivo and in vitro." (PMID 39834933, 2024). "Our findings suggest that AURKA may contribute to the progression of liver fibrosis by enhancing HSC activation and proliferation while inhibiting HSC apoptosis." (PMID 39834933, 2024). "This study reveals that AURKA expression is significantly upregulated in the liver tissues of patients with alcohol-related liver fibrosis, as well as in liver tissues from mouse models of acetaldehyde and carbon tetrachloride-induced liver fibrosis, and in HSCs stimulated by acetaldehyde." (PMID 39834933, 2024). "This study demonstrates that AURKA expression is elevated in activated HSCs and liver fibrosis." (PMID 39834933, 2024). "In addition, AURKA expression was markedly increased in patients with liver fibrosis and a history of alcohol consumption compared to normal liver tissues." (PMID 38590119, 2024). "Additionally, immunohistochemistry staining demonstrated a significant upregulation of AURKA in human liver fibrosis and cirrhosis tissues compared to normal liver tissues." (PMID 39834933, 2024). "However, few studies have investigated the relationship between AURKA and liver fibrosis." (PMID 39834933, 2024). "Thus, the authors hypothesized a potential positive role of AURKA in aggravating alcohol‐related liver fibrosis." (PMID 38590119, 2024). "Aurora kinase A (AURKA) has been shown to facilitate HSC activation and liver fibrosis through the Wnt/β-catenin pathway, suggesting a potential therapeutic target for fibrosis management." (PMID 40350059, 2026). "While previous studies have delineated AURKA’s involvement in HCC and PMF, its role in liver fibrosis remains underexplored." (PMID 39834933, 2024). "To explore the role of AURKA in ALF, we detected the protein expression of AURKA in patients with liver fibrosis and a history of alcohol consumption, and in HSC-T6 and LX-2 cells stimulated by acetaldehyde." (PMID 36778123, 2023). "In conclusion, AURKA may promote HSC activation and liver fibrosis through the Wnt/β-catenin pathway, suggesting its potential as a therapeutic target for liver fibrosis." (PMID 39834933, 2024).
liver fibrosis (continued). "Our findings suggest that AURKA may enhance HSC activation and liver fibrosis through the Wnt/β-catenin pathway, indicating its potential as a therapeutic target for liver fibrosis." (PMID 39834933, 2024). "This study indicates that targeting AURKA could offer a promising therapeutic strategy for liver fibrosis, providing good tolerability and safety in the absence of approved treatments." (PMID 39834933, 2024). "Our study revealed that AURKA expression increases with the progression of liver fibrosis and is positively correlated with ACTA2, a marker of activated HSCs, as well as the fibrogenic genes COL1A1 and TIMP1, based on publicly available gene expression datasets from liver fibrosis patients." (PMID 39834933, 2024). "Treatment with the AURKA inhibitor MLN8237 effectively reduced hepatic fibrosis and HSC activation, thereby improving liver function in a CCl4-induced mouse model of liver fibrosis, without significant adverse effects." (PMID 39834933, 2024).
mesothelioma (4 papers, 2009 to 2021). A usually malignant and aggressive neoplasm of the mesothelium which is often associated with exposure to asbestos. "AURKA is overexpressed in several cancers, and has been associated with shorter survival in mesotheliomas and small molecule inhibitors of AURKA are currently in phase II trials." (PMID 22905093, 2012). "AURKA is overexpressed in several cancers, and has been associated with shorter survival in mesotheliomas." (PMID 19662092, 2009). "In another study, microarray analyses of pleural mesotheliomas revealed that the more aggressive mesotheliomas expressed increased levels of AURKA and AURKB and functionally related genes involved in cell cycle control and mitosis." (PMID 33202573, 2020). "In human mesothelioma tissues, Crispi’s group found upregulated levels of AURKA and related genes as well as increased amounts of both AURKA and AURKB in five mesothelioma cell lines indicating a potential involvement of Aurora kinases in the oncogenesis of MPM." (PMID 33202573, 2020). "Likewise, ZM447439, an Aurora kinase inhibitor, has shown effective inhibition of both AURKA and AURKB activities via reduction in histone H3 phosphorylation, resulting in decreased cell growth in mesothelioma cell lines." (PMID 33202573, 2020).
myelofibrosis (4 papers, 2020 to 2025). A partial or complete replacement of the bone marrow stroma by fibrous tissue. "Importantly, deletion of one allele that encodes aurora kinase A completely abrogated myelofibrosis in a murine MPN model, providing clear genetic evidence that decreasing aurora kinase A activity may provide therapeutic benefit in MF." (PMID 32823910, 2020). "Moreover, the selective inhibition of AURKA has significantly reduced TGF-β levels and attenuated renal fibrosis and primary myelofibrosis in vivo in mouse models." (PMID 40872590, 2025). "This is of interest as AURKA is the target for alisertib (MLN8237), which was recently demonstrated to promote megakaryocyte polyploidization and ameliorate the myelofibrosis phenotype in mouse models, with some efficacy also in patients with myelofibrosis." (PMID 32386542, 2020).
neuroendocrine tumors (4 papers, 2013 to 2024). "Several AURKA inhibitors have demonstrated anti-proliferative efficacy in preclinical models of neuroendocrine tumors by disrupting the MYCN-AURKA complex." (PMID 38016952, 2023).
rhabdoid tumor (4 papers, 2018 to 2022). An aggressive malignant embryonal neoplasm usually occurring during childhood. "Some studies have demonstrated the efficacy of EZH2 and AURKA inhibitors in patients with rhabdoid tumors, also defined by the loss of SMARCB1." (PMID 35406448, 2022). "In rhabdoid tumor (RT) cells and normal fibroblast cells, INI1/hSNF5 complex associates with the AURKA promoter and represses AURKA transcription." (PMID 33451333, 2021).
serous ovarian cancer (4 papers, 2016 to 2024).
small cell lung carcinoma (4 papers, 2020 to 2024). Small cell lung cancer (SCLC) is a highly aggressive malignant neoplasm, accounting for 10-15% of lung cancer cases, characterized byrapid growth, and early metastasis. "In a phase II study, an AURKA inhibitor as monotherapy achieved a 21% objective response rate in patients with relapsed or refractory small-cell lung cancer." (PMID 39085197, 2024).
acute megakaryocytic leukemia (3 papers, 2014 to 2021). "MLN8237 (Alisertib), a selective inhibitor of AURKA, induced polyploidization and expression of mature megakaryocyte markers in acute megakaryocytic leukemia." (PMID 34715887, 2021).
atherosclerosis (3 papers, 2023 to 2024). A disease characterized by the build-up of fatty material and calcium deposition in the arterial wall resulting in partial or complete occlusion of the arterial lumen. "Among the LAA stroke ecDNA unique genes, there were two hub genes significantly associated with atherosclerosis, including RNA polymerase II subunit C (POLR2C) and Aurora kinase A (AURKA)." (PMID 38506071, 2024). "Up‐regulation of AURKA resulted in dysregulated functions of endothelial cells and vascular smooth muscle cells, and promoted progression of atherosclerosis." (PMID 38506071, 2024). "In vascular disease, atherosclerosis, the potential role of AURKA on endothelial cell dynamics has been implied." (PMID 36977984, 2023). "Their study revealed the central effect of the Linc00299/miR‐490‐3p/AURKA axis on the regulation of cell proliferation and migration in atherosclerosis." (PMID 37706018, 2023). "In atherosclerosis, the upregulated AURKA could promote the proliferation and migration of umbilical vein endothelial cells, which was similar to our results." (PMID 36977984, 2023).